NOX4 (NADPH oxidase 4)
Diseases named in the same sentence as NOX4 in open-access papers (continued):
Sharing a sentence is not in itself a finding about the gene and the disease.
primary biliary cholangitis (3 papers, 2020 to 2023). Primary biliary cholangitis (PBC) is a chronic and slowly progressive cholestatic liver disease of autoimmune etiology characterized by injury of the intrahepatic bile ducts that may eventually lead to liver failure. "The NOX1/ NOX4 inhibitor setanaxib, which indirectly affects ENaC, is tested in clinical phase 2 and 3 trials for therapy of primary biliary cholangitis, liver stiffness and squamous cell carcinoma of the head and neck." (PMID 37175488, 2023). "Moreover, a phase II clinical trial examined the effect of GKT137831, an inhibitor of NOX4, in patients with Primary Biliary Cholangitis (PBC), but until now, there have been no data available." (PMID 33407885, 2021).
psoriasis (3 papers, 2019 to 2025). An autoimmune condition characterized by red, well-delineated plaques with silvery scales that are usually on the extensor surfaces and scalp. "The search in PheGenI and EMBL-EBI databases didn’t reveal any NOX4 polymorphism associated with psoriasis." (PMID 31752190, 2019). "Similarly, NOX4, CDK5, FLT3, ER‐α, and CDK1 are targets for psoriasis treatment." (PMID 41323822, 2025).
retinal diseases (3 papers, 2015 to 2025). "Our results suggest that Nox4 is potentially implicated in retinal vasculature development and contributes to aberrant blood vessel growth in neovascular retinal diseases through regulation of the VEGF/VEGFR2 pathway." (PMID 25866826, 2015). "Taken together, these results suggest that Nox4 plays a causal role in retinal angiogenesis and inhibition of Nox4 may provide a novel therapeutic strategy for neovascular retinal diseases." (PMID 25866826, 2015). "Reducing retinal Nox4 expression may represent a promising therapeutic approach for neovascular retinal diseases such as PDR." (PMID 25866826, 2015).
rheumatoid arthritis (3 papers, 2021 to 2023). A chronic, systemic autoimmune disorder characterized by inflammation in the synovial membranes and articular surfaces. "Inhibition of NOX4 and inactivation of JNK helped to mitigate the inflammatory response in fibroblast-like synoviocytes, exerting protective effects against the progression of rheumatoid arthritis." (PMID 33744854, 2021).
tauopathy (3 papers, 2024 to 2025). Neurodegenerative disorders involving deposition of abnormal tau protein isoforms (tau proteins) in neurons and glial cells in the brain. "In fact, NOX-4 and -2 downregulation/deficiency were seen to decrease tauopathy load in mice." (PMID 39721496, 2025). "NOX4 has been linked to oxidative stress and tauopathies in neurodegenerative diseases." (PMID 39469453, 2024). "Tau aggregation was further seen to activate NOX pathway machinery, especially NOX-4 expression which is widely expressed in neurons, and reported to be increased in human AD brains with hyperphosphorylated tau and mouse models with tauopathies." (PMID 39721496, 2025).
tuberculosis (3 papers, 2021 to 2022). A chronic, recurrent infection caused by the bacterium Mycobacterium tuberculosis. "We were interested in the role of NOX4 in the tumor microenvironment changed by tuberculosis fibrosis." (PMID 33567693, 2021).
abdominal aortic aneurysm (2 papers, 2016 to 2025). Enlargement and ballooning of the vessel that supplies arterial blood to the abdomen, pelvis and legs. "In addition, Nox4 expression was decreased in human abdominal aortic aneurysm in spite of increased oxidative stress." (PMID 27200147, 2016). "MFG-E8 promotes oxidative stress by upregulating NOX4 and activating the MAPK pathway, which increases ROS production and affects vascular smooth muscle cell (VSMC) apoptosis, thereby driving the progression of abdominal aortic aneurysm (AAA)." (PMID 40706634, 2025).
aneurysm (2 papers, 2021). Bulging or ballooning in an area of an artery secondary to arterial wall weakening. "The secondary increase of TGF-β and NOX4-induced dysregulation of hypoxia-inducible factor-1 (HIF-1α)/vascular endothelial factor (VEGF) signaling further contributes to aneurysm progression." (PMID 33807627, 2021).
Anxiety (2 papers, 2024 to 2025). Intense feelings of nervousness, tension, or panic often arise in response to interpersonal stresses. "Activation of HDAC1, HDAC3, and NADPH oxidase 4 (NOX4) influences prostaglandin production in the cortex via microglia, which is associated with heightened anxiety and altered glutathione metabolism." (PMID 39851502, 2025).
aortic valve stenosis (2 papers, 2020 to 2025). Aortic valve stenosis (AVS) is a condition characterized by narrowing of the heart's aortic valve opening. "In contrast, a study suggested that NOX4 deficiency may contribute to adverse myocardial remodeling, as NOX4 expression was abnormally reduced in patients with severe aortic valve stenosis and pressure overload." (PMID 41009041, 2025). "Likewise, our team demonstrated that in Angptl2-knockdown mouse model exhibiting mild aortic valve stenosis and LV systolic dysfunction, cardiac-specific deletion of NOX4 using AAV9-sh-NOX4 attenuated LV contractile dysfunction and increased cardiac antioxidant response." (PMID 41009041, 2025).
astrocytoma (2 papers, 2025 to 2026). "Low NOX4 expression values increased the probability of predicting astrocytoma, as a negative correlation is observed between the SHAP values for the astrocytoma class and gene expression." (PMID 40867242, 2025).
brain edema (2 papers, 2020 to 2025). Increased intracellular or extracellular fluid in brain tissue. "The impairment of blood-brain barrier function after ICH can lead to the aggravation of persistent cerebral oedema; thus, we measured the cerebral water content and found that NOX4 knockdown substantially reduced the cerebral water content in rats and alleviated the degree of oedema." (PMID 33281556, 2020).
cardiac interstitial fibrosis (2 papers, 2020 to 2021). "In cardiac-specific human NADPH oxidase 4 (Nox4) transgenic mice, an increase in NOX4 protein expression leads to an increase in ROS generation with cardiac interstitial fibrosis through activation of protein kinase B-mechanistic target of rapamycin (Akt-mTOR) and NF-κB signaling pathways." (PMID 34297135, 2021).
coronary atherosclerosis (2 papers, 2022 to 2026). Atherosclerosis of the coronary vasculature. "Further data analysis and meta-analysis revealed that NOX4 gene expression was significantly upregulated in patients with CHD (P<.05), which may be related to coronary atherosclerosis and myocardial injury." (PMID 41578467, 2026).
cytomegalovirus infection (2 papers, 2018 to 2025). A herpesvirus infection caused by Cytomegalovirus. "Factors and reactive species implicated in hearing loss included cytomegalovirus infection, genetic polymorphisms, NADPH oxidase 4 (NOX4), NOX transgenic models (NOX-Tg), lipid hydroperoxides (LOOH), and malondialdehyde (MDA)." (PMID 41462597, 2025). "In patients with EH specifically, CRP, TNF-α, NOX4, 8-OHDG, eNOS, and Ang II were associated with HCMV infection in all models (P<0.05)." (PMID 29752343, 2018). "Accordingly, our result demonstrated that NOX4 and 8-OHDG levels were significantly increased in hypertensive subjects, simultaneously in those with HCMV infection." (PMID 29752343, 2018).
Duchenne muscular dystrophy (2 papers, 2022 to 2025). Duchenne muscular dystrophy (DMD) is a neuromuscular disease characterized by rapidly progressive muscle weakness and wasting due to degeneration of skeletal, smooth and cardiac muscle. "The current study investigated targeting NAD(P)H oxidase 4 (NOX4) as a potential strategy to reduce fibrosis and promote regeneration in disease-burdened muscle that models Duchenne muscular dystrophy (DMD)." (PMID 36278481, 2022).
esophageal adenocarcinoma (2 papers, 2017 to 2022). A malignant tumor with glandular differentiation arising predominantly from Barrett mucosa in the lower third of the esophagus. "No major studies, to date, have focused primarily on NOX4 in esophageal adenocarcinoma or squamous cell carcinoma." (PMID 28578276, 2017).
esophageal carcinoma (2 papers, 2017 to 2021). A primary or metastatic malignant neoplasm involving the esophagus. "Similarly, esophageal carcinoma samples showed a differential expression of NOX4 antigen relative to its corresponding non-neoplastic esophageal mucosa (>75% of the adenocarcinoma and >50% of the squamous carcinoma cases were high positive)." (PMID 28578276, 2017).
glaucoma (2 papers, 2020 to 2021). Increased pressure in the eyeball due to obstruction of the outflow of aqueous humor. "As such, pharmacological inhibition of Nox4 would be a viable therapeutic strategy for the control of scarring after glaucoma surgery." (PMID 33202904, 2020).
hemangioendothelioma (2 papers, 2016 to 2017). A vascular proliferation characterized by the presence of prominent endothelial cells and the formation of vascular channels. "This was due to the fact that, in hemangioendothelioma cells, Nox4 delivers H2O2 to the nuclear compartment causing oxidative alteration of DNA." (PMID 27774507, 2016). "It was found that only the Nox4 isoform was present in endothelial cell tumors cells whereas knockdown of Nox4 gene remarkably decreased the expression of MCP-1 as well as hemangioendothelioma formation." (PMID 27774507, 2016). "miRNAs can also affect the NOX4-MCP-1 axis critical for hemangioendothelioma; silencing of the enzyme required for miRNA maturation (Dicer) prevented formation of tumors in vivo, accompanied by the upregulation of miR-21a-3p activity targeting the 3′UTR of the NOX4 transcript." (PMID 28626501, 2017).
hemangioma (2 papers, 2011 to 2022). A benign vascular lesion characterized by the formation of capillary-sized or cavernous vascular channels. "In hemangioma, fulvene-5 impairs NOX4 activity and inhibits hemangioma growth in vivo." (PMID 35646942, 2022). "Furthermore, a recent study showed that inhibitors specific for NOX4 and NOX2 blocked hemangioma (i.e. endothelial cell-derived tumor) growth in vivo." (PMID 21326871, 2011).
hyperphosphataemia (2 papers, 2021 to 2025). "AMPK inactivation by hyperphosphataemia induces OS via NOX4-dependent NADPH oxidase activation, increasing ROS production and triggering TGFβ-1 signalling through SMAD3 phosphorylation, which promotes ECM accumulation in human mesangial cells." (PMID 40298783, 2025). "In aged mice, hyperphosphataemia was correlated with a significant increase in ROS production and elevated Nox4 expression in the aorta compared with young mice." (PMID 40298783, 2025). "Additionally, aged mice exhibited reduced expression of Nrf2 and the antioxidant enzymes Sod2-Mn and Gpx1, indicating that hyperphosphataemia contributes to age-related vascular dysfunction by activating Nox4, thereby promoting redox imbalance and OS." (PMID 40298783, 2025). "Old mice showed a significant increase in Nox4 expression, which was blocked with the low P diet, suggesting that aging-related hyperphosphatemia could mediate ROS production through Nox4 activation." (PMID 34439556, 2021).
ischemic cardiomyopathy (2 papers, 2017 to 2025). Ischemic cardiomyopathy is a cardiomyopathy in which a weakness in the muscle of the heart due to inadequate oxygen delivery to the myocardium with coronary artery disease being the most common cause. "Western blot analysis showed up-regulation of the full-length NOX4 in ischemic cardiomyopathy samples and confirmed presence of shorter isoforms both in control and failing samples with disease-associated expression pattern." (PMID 29204124, 2017). "Finally, hearts from patients with ischemic cardiomyopathy showed increased NOX4 expression and oxidative stress, compared to control nonfailing hearts." (PMID 41009041, 2025).
kidney failure (2 papers, 2021 to 2023). An acute or chronic condition that is characterized by the inability of the kidneys to adequately filter the blood. "Regarding the functional significance of Nox subtypes up-regulation, in a previous comprehensive study, it was demonstrated that the induction of Nox4 rather than Nox1 or Nox2 is implicated in ROS overproduction and oxidative stress-induced kidney failure." (PMID 34572988, 2021).
Knee Osteoarthritis (2 papers, 2021 to 2023). "Induction of knee osteoarthritis caused a loss in muscle coordination, knee swelling, elevations in the inflammatory mediators (TNF-α & TGF-β1), and the oxidative stress markers (MMP-13 & NOX-4) in joint tissues." (PMID 37878123, 2023).
leukemia (2 papers, 2014 to 2022). A malignant (clonal) hematologic disorder, involving hematopoietic stem cells and characterized by the presence of primitive or atypical myeloid or lymphoid cells in the bone marrow and the blood. "Taken together, these in vitro results suggest that NOX4 is relevant under conditions of leukemia cell competition in FLT3-mutated cell lines." (PMID 35348887, 2022). "Targeting Nox4 may therefore result in leukemia inhibitory or promoting effects and underlines the necessary caution in developing NOX4-modulating drugs." (PMID 35348887, 2022). "Detailed pre-clinical genetic and pharmacologic studies of NOX4 modulation are clearly required before defining it as a bona fide target in leukemia therapy." (PMID 35348887, 2022). "We previously showed that Nox-derived ROS are involved in sustaining the high glucose uptake observed in B1647 cells; subsequently, we demonstrated that VEGF-induced ROS derived from Nox2 and Nox4 play a prosurvival role in the leukemia cell line." (PMID 24738074, 2014). "The phenotype observed here suggests that the role of Nox4 in leukemia is highly context dependent." (PMID 35348887, 2022). "However, we observed rather subtle effects of NOX4 and p22-phox deletion on leukemia cell proliferation or apoptosis compared to cell competition and negative selection assays." (PMID 35348887, 2022).
liver cirrhosis (2 papers, 2021 to 2022). "Although higher levels of both NOX2 and NOX4 in hepatic tumor cells have been positively correlated with liver cirrhosis, further studies are necessary to ascertain whether NOX2 and NOX4 increase is involved in the transition from liver cirrhosis to HCC." (PMID 34204571, 2021).
Marfan syndrome (2 papers, 2021 to 2025). A disorder of the connective tissue. "The NOX4 isoform impacts the progression of the aortic dilation in Marfan syndrome, the structural organization of the aortic tunica media, and the vascular smooth muscle cells’ phenotypic modulation." (PMID 34440716, 2021).
mesothelioma (2 papers, 2014 to 2022). A usually malignant and aggressive neoplasm of the mesothelium which is often associated with exposure to asbestos. "As noted, both apocynin and Nox4 anti-sense treatment markedly alleviated the toxicity of extracellular ascorbate to mesothelioma cells." (PMID 25279352, 2014).
multinodular goiter (2 papers, 2021). Nodular goiter characterized by more than one discrete tissue mass. "In paranodular tissues of multinodular goiter considered as controls, NOX4 protein expression was low in hypofunctional follicles while the active follicles revealed greater staining." (PMID 33916948, 2021). "Compared to control paranodular thyroid tissues of multinodular goiters, the majority of the follicles from GD thyroids showed increased expression of NOX4 in thyrocyte’s cytoplasm." (PMID 35008579, 2021).
myelodysplastic syndrome (2 papers, 2014 to 2019). A clonal hematopoietic disorder characterized by dysplasia and ineffective hematopoiesis in one or more of the hematopoietic cell lines. "Findings on the role of Nox4 in nuclear ROS production highlight the molecular mechanisms (at the level of the cell nucleus) responsible for genomic instability in myelodysplastic syndromes." (PMID 31814865, 2019).
neuropathy (2 papers, 2011 to 2024). A disorder affecting the nervous system that manifests with pain, tingling, numbness, and/or muscle weakness. "Furthermore, the activation of SIRT1 by HES promoted the inhibition of NADPH oxidase-4 (NOX4) expression and protection against oxidative and inflammatory damage characterizing an in vivo model of neuropathy." (PMID 38396635, 2024).
osteosarcoma (2 papers, 2018 to 2025). A usually aggressive malignant bone-forming mesenchymal neoplasm, predominantly affecting adolescents and young adults. "Their nanocomposite hydrogel delivered an NADPH oxidase 4 (Nox4) inhibitor followed by doxorubicin, reprogramming the stromal environment and boosting Anti-Programmed Cell Death Protein 1 (PD–1) responses in osteosarcoma models." (PMID 40940809, 2025). "In the 3 osteosarcoma-derived osteogenic cell lines (MG-63, Cal-72, and SaOs-2) investigated here, the NOX4 expression levels correlated well with the cells migration capacity." (PMID 30065198, 2018).
overnutrition (2 papers, 2020 to 2022). An imbalanced nutritional status resulting from excessive intake of nutrients. "In the myocardium, early overnutrition was associated with a significant increase in the gene expression of the proinflammatory markers IL-1β (p < 0.05), IL-6 (p < 0.01), TNF- α (p < 0.05), and LO (p < 0.05), and the pro-oxidant enzymes NOX-1 (p < 0.05) and NOX-4 (p < 0.01)." (PMID 32093229, 2020).
Peritoneal Fibrosis (2 papers, 2022 to 2023). Disorder characterized by a wide range of structural changes in PERITONEUM, resulting from fibrogenic or inflammatory processes. "Scarcely information is available on the role of NOX4 in peritoneal fibrosis." (PMID 35453560, 2022). "To further investigate the antioxidant effect of D-4F in preventing peritoneal fibrosis, we examined the activity of CuZn-SOD and Px-GSH in serum and the protein expression of NOX2 and NOX4 in peritoneal tissue of PF rats." (PMID 37576813, 2023).
prostate tumors (2 papers, 2018 to 2025). "Elevated expression of NOX4 has been demonstrated to promote fibroblast activation and facilitate stromal-epithelial interactions, thereby contributing to the progression of prostate tumors." (PMID 41346575, 2025). "In addition, NOX4 gene expression was markedly elevated in human metastatic prostate cancers, but not in primary prostate tumours." (PMID 30459931, 2018).
renovascular hypertension (2 papers, 2018 to 2022). High blood pressure secondary to renal artery stenosis. "Furthermore, the RAS-inhibitory and antioxidant properties of nobiletin resolved renal injury in a manner related to the AT1R/Nox4 pathway in renovascular hypertensive rats." (PMID 35662276, 2022).
retinal ischemia (2 papers, 2017 to 2024). A ischemic disease that involves the retina. "We explored the relative role of the different NOX and found that, similar to other retinal ischemia models, in the B6N strain but not in B6J, NOX4 contributed to the ROS generation in photoreceptors under HIPR." (PMID 28671996, 2017).
retinoblastoma (2 papers, 2021 to 2022). A malignant tumor that originates in the nuclear layer of the retina. "Another assessment of NOX in clinical samples comes from the profiling of NOX4 protein expression in different grades of excised ocular tumours and, NOX4 expression is found to be correlated to higher grade retinoblastoma and massive choroidal invasion." (PMID 33557289, 2021).
schizophrenia (2 papers, 2022 to 2023). A major psychotic disorder characterized by abnormalities in the perception or expression of reality. "A study showed significant increased expression of NOX4 in patients with schizophrenia." (PMID 37511534, 2023). "Alterations in NOX4 expression in schizophrenia are seemed to be poorly investigated." (PMID 35696356, 2022). "There is the only mention of NOX4 RNA levels in the brain cells of deceased schizophrenia patients." (PMID 35696356, 2022). "In the present study, we analyzed the distribution and the average NOX4 protein levels, DNA damage markers (8-oxodG and γH2AX), as well as BAX1, BCL2 and NRF2 proteins in the PBL of schizophrenia patients and healthy controls." (PMID 35696356, 2022).